SGTA (small glutamine rich tetratricopeptide repeat co-chaperone alpha)
Description:
Co-chaperone that binds misfolded and hydrophobic patches-containing client proteins in the cytosol. Mediates their targeting to the endoplasmic reticulum but also regulates their sorting to the proteasome when targeting fails. Functions in tail-anchored/type II transmembrane proteins membrane insertion constituting with ASNA1 and the BAG6 complex a targeting module. Functions upstream of the BAG6 complex and ASNA1, binding more rapidly the transmembrane domain of newly synthesized proteins. It is also involved in the regulation of the endoplasmic reticulum-associated misfolded protein catabolic process via its interaction with BAG6: collaborates with the BAG6 complex to maintain hydrophobic substrates in non-ubiquitinated states. Competes with RNF126 for interaction with BAG6, preventing the ubiquitination of client proteins associated with the BAG6 complex. Binds directly to HSC70 and HSP70 and regulates their ATPase activity. (Microbial infection) In case of infection by polyomavirus, involved in the virus endoplasmic reticulum membrane penetration and infection via interaction with DNAJB12, DNAJB14 and HSPA8/Hsc70.
Synonyms: UBP; SGT; SGT1; Vpu; hSGT; alphaSGT
Tractability: PROTAC: ubiquitination databases record sites on it; its protein half-life has been measured.
Gene: Protein-coding gene on chromosome 19 (2,754,711 to 2,783,390, reverse strand). Ensembl gene ENSG00000104969.
Subcellular location: Cytoplasm; Nucleus
Subcellular location (Human Protein Atlas): Nucleoplasm
Pathways (Reactome):
Protein localization: Insertion of tail-anchored proteins into the endoplasmic reticulum membrane
Gene Ontology:
Molecular function: BAT3 complex binding; identical protein binding; protein binding; molecular adaptor activity
Biological process: ERAD pathway; negative regulation of ERAD pathway; negative regulation of ubiquitin-dependent protein catabolic process; positive regulation of ERAD pathway; positive regulation of ubiquitin-dependent protein catabolic process; tail-anchored membrane protein insertion into ER membrane; post-translational protein targeting to endoplasmic reticulum membrane
Cellular component: cytoplasm; cytosol; membrane; nucleoplasm; nucleus; TRC complex
Genetic constraint (gnomAD): Loss-of-function variants: 20 observed, 38.88 expected, observed/expected ratio (o/e) 0.51, 90% interval 0.36 to 0.75. The upper end of that interval is the gene's LOEUF score, 0.75, which puts it in group 3 of 6, group 1 being the genes least tolerant of losing a copy. Missense variants: 341 observed, 419.95 expected, observed/expected ratio (o/e) 0.81, 90% interval 0.74 to 0.89. Synonymous variants: 174 observed, 170.64 expected, observed/expected ratio (o/e) 1.02, 90% interval 0.9 to 1.16.
Homologues: Orthologues: macaque SGTA (99% identical), chimpanzee SGTA (99% identical), guinea pig SGTA (90% identical), mouse Sgta (89% identical), rat Sgta (89% identical), dog SGTA (76% identical), tropical clawed frog sgta (75% identical), pig SGTA (74% identical), zebrafish sgta (69% identical), Drosophila melanogaster unc-45 (12% identical), Caenorhabditis elegans unc-45 (11% identical). Paralogues in human: SGTB (58% identical), RPAP3 (20% identical), TTC4 (19% identical), TTC1 (18% identical), SPAG1 (17% identical), TTC31 (17% identical), SPATA16 (17% identical), ST13 (17% identical), STIP1 (16% identical), STUB1 (16% identical), SUGT1 (15% identical), UNC45A (15% identical), and 6 more.
Diseases named in the same sentence as SGTA in open-access papers:
SGTA is named in the same sentence as 15 diseases in open-access papers, as found by Europe PMC text mining. Sharing a sentence is not in itself a finding about the gene and the disease. The quoted sentences say what the papers report.
prostate carcinoma (3 papers, 2016 to 2022). A carcinoma that arises from epithelial cells of the prostate gland. "We showed that cytoplasmic REIC/DKK-3 interferes with the dimerization of SGTA and abolishes the function of SGTA as a negative regulator of the AR, resulting in enhanced AR sensitivity in human prostate cancer cells." (PMID 26658102, 2016). "The REIC/Dkk-3 and SGTA proteins are structurally and functionally well-conserved between human and dog; thus, our results regarding the interaction of these molecules in androgen-independent prostate cancer of human and dogs are applicable to both species." (PMID 28599655, 2017). "Recently, we showed that SGTA is expressed in canine prostate cancer but not in prostate hyperplasia." (PMID 28599655, 2017). "According to these authors, PC cells may exhibit high levels of expression of the small glutamine-rich tetratricopeptide repeat-containing protein alpha (SGTA), a molecule involved in the inhibition of AR signaling in androgen-independent human and canine prostate cancer cells." (PMID 35681707, 2022).
bipolar disorder (1 paper, 2015). A disorder of the brain that causes unusual shifts in mood, energy, activity levels and the ability to carry out day-to-day tasks. "We identified three rare deletions in KCNJ6, UNC13C, OTOL1 and 7 rare duplications in CNTNAP2/MIR548F3, CORO7/VASN, DTNB, EMID2, KCNF1, PDPR and SGTA/THOP1 that are present in children with bipolar disorder (and their parents)." (PMID 25887117, 2015).
prostate adenocarcinoma (1 paper, 2016). "As a result, from the normal heart and prostate adenocarcinoma cDNA libraries, SGTA was found to be a novel protein that interacts with full-length human REIC/DKK-3 (normal heart result)." (PMID 26658102, 2016).
viral infection (1 paper, 2016). "In addition to SV40 and BK PyV, SGTA also plays a role in other viral infection pathways, such as in HIV, parvovirus, and severe acute respiratory syndrome coronavirus infections, all of which have structural proteins that interact with SGTA’s central tetratricopeptide (TPR) domain repeats." (PMID 27589785, 2016).
cancer (4 papers, 2016 to 2025). A tumor composed of atypical neoplastic, often pleomorphic cells that invade other tissues. "Our data show a novel non-genetic mechanism to inhibit apoptosis and suggest PDIA4, DNAJB12/14, and SGTA as novel therapeutic targets to rescue apoptosis and inhibit proliferation in cancer cells." (PMID 41120732, 2025). "Thus, the interaction of REIC/DKK-3 with SGTA and TCTEX-1 is implicated in cancer-related signaling suppressed by the tumor suppressor REIC/DKK-3." (PMID 26658102, 2016). "Together, these findings establish that DNAJB12, DNAJB14, and SGTA are required for PDIA4 reflux to the cytosol, where it binds caspase-3 and promotes cancer cell resistance." (PMID 41120732, 2025). "Thus, targeting the DNAJB12/14-HSC70/SGTA axis is a promising strategy to inhibit ERCYS and impair cancer cell fitness." (PMID 40202782, 2025).
infection (2 papers, 2015 to 2020). The state of being infected such as from the introduction of a foreign agent such as serum, vaccine, antigenic substance or organism. "This stimulation requires Hsp105’s nucleotide exchange activity as overexpressing Hsp105 NE*-F or G*-F did not robustly enhance infection (compare third and fourth bars to second bar), and is specific because overexpressing neither Hsc70, SGTA, nor HspBP1 stimulated infection." (PMID 26244546, 2015).
neurodegenerative disease (2 papers, 2015 to 2022). A disorder of the central nervous system characterized by gradual and progressive loss of neural tissue and neurologic function. "Interestingly, a recent study showed that SGTA, which senses hydrophobic transmembrane domains in TA proteins also associates with intracellular aggregates associated with neurodegenerative diseases." (PMID 35542047, 2022). "We selected HSPA8, CLINT1 and SGTA as candidate proteins that could potentially be recruited into pathological aggregates in neurodegenerative disease." (PMID 26317359, 2015).
SGTA also shares sentences with these, for which no sentence is quoted: atherosclerosis (1 paper); colorectal cancer (1); lung carcinoma (1); Myeloma (1); oral candidiasis (1); prostate hyperplasia (1); psychosis (1); tumor (1).